CDK7 (cyclin dependent kinase 7)
Diseases named in the same sentence as CDK7 in open-access papers (continued):
Sharing a sentence is not in itself a finding about the gene and the disease.
cancer (continued). "Recent reports suggest the role of nonsynonymous single nucleotide polymorphisms (nsSNPs) in cyclin-dependent kinase 7 (CDK7) gene associated with defect in the DNA repair mechanism that may contribute to cancer risk." (PMID 23561625, 2013). "However, a pan-cancer study across different epithelial tumor types revealed significant recurrent loss-of-function alterations in CDK7, including recurrent copy-number loss in four epithelial cancer types: ovarian serous, prostate and esophageal carcinoma and cholangiocarcinoma." (PMID 39800748, 2025). "Thus, read-through, relative increase of NEAT1_2 expression, or NEAT1_2 splicing upon CDK7 inhibition could be linked to susceptibility of cancer cell lines to CDK7 inhibition." (PMID 36279270, 2022). "Despite playing critical roles in general transcription, inhibition of CDK7 and BRD4 have been implicated in preferential downregulation of cancer-related genes, such as MYC, thereby selectively killing cancer cells." (PMID 41505030, 2026). "Significant attention has been paid to the role that transcriptional CDKs play in cancer, including CDK7, CDK8, CDK9, CDK12, and CDK13." (PMID 40361480, 2025). "In ICC cell lines, THZ1-mediated inhibition of CDK7 decreased cell proliferation, stopped the cell cycle, and prevented cancer cell migration and invasion." (PMID 40361480, 2025). "CDK7 has emerged as a cancer target because of its pivotal roles in cell cycle progression and transcription." (PMID 40921851, 2025). "Based on the notion of “transcriptional addiction,” targeting transcription regulators, including CDK7, has emerged as a powerful strategy to attenuate cancer dependency, particularly in cancers that rely on SE-driven genes (e.g., MYC, RUNX2, SOX2, SOX9)." (PMID 39800748, 2025). "Several CDK inhibitors are already in use in cancer research, and two inhibitors of Cdk7 are currently in clinical trials." (PMID 39870514, 2025). "Pharmacologic inhibition of CDK7 has emerged as a promising option for cancer treatment (see Section 9, Is TFIIH an Attractive Drug Target)?" (PMID 40004560, 2025). "The discovery of promising anti-cancer drugs targeting XPB and CDK7 has confirmed TFIIH as a viable target for developing the next generation of small-molecule anti-cancer drugs." (PMID 40004560, 2025). "CDK7’s dual role in transcription and cell cycle regulation makes this kinase an attractive drug target in cancer therapy." (PMID 40004560, 2025). "Genome-wide screening using CRISPR has identified that CDK7 inhibitors, such as samuraciclib, are key determinants in inducing cancer cell senescence, particularly through the mTOR signaling pathway." (PMID 40149983, 2025). "One effective method for reducing the aggressiveness of cancer is to inhibit CDK7-dependent transcriptional addiction in the disease." (PMID 40361480, 2025). "Studies show that reducing CDK7 activity in cancer cells, either genetically or pharmacologically, decreases cell proliferation, making CDK7 a promising therapeutic target in oncology." (PMID 41347148, 2025). "SEs play key roles in maintaining cancer cell identity and promoting oncogenic transcription, our group had reported that inhibition of SEs-related proteins RARα and CDK7 exerts anti-TNBC effects." (PMID 41173847, 2025). "CDK7 has also become a target for small-molecule inhibitors, showing promise in the treatment of cancer and inflammation." (PMID 38540292, 2024). "CDK7’s vital role in the preservation of malignant phenotypes across various cancer cells is underscored by substantial evidence." (PMID 38605321, 2024). "The development of nanoparticle-based strategies for CDK7 targeting offers promising avenues for cancer therapy." (PMID 39209834, 2024). "Overall, these findings underscore CDK7 as a critical mediator in cancer pathogenesis and opens avenues for targeted therapeutic interventions, thus heralding a new frontier in cancer research." (PMID 38605321, 2024).
cancer (continued). "THZ2 is an analogue of THZ1 with a five-fold increased half-life, which effectively inhibits the growth of various cancer cells by inhibiting CDK7 as potent as THZ1, including breast cancer and osteosarcoma." (PMID 38540292, 2024). "The effectiveness of CDK7 inhibition has been demonstrated in various aggressive cancer types, including small-cell lung cancer, triple-negative breast cancer (TNBC), MYCN-amplified neuroblastoma, osteosarcoma and pancreatic ductal adenocarcinoma." (PMID 38844984, 2024). "Preclinical studies have shown that CDK7 inhibitors execute anti-cancer function partly depending on the repression of transcription, particularly transcription of super-enhancer-associated genes in cancer." (PMID 38566153, 2024). "Accumulating evidence indicates that CDK7 is often overexpressed, and its activity is enhanced in a variety of cancers, thereby contributing to aberrant proliferation of cancer cells." (PMID 39202439, 2024). "Ibulocydine (IB) is a novel (cyclin-dependent kinase) CDK7/9 inhibitor prodrug displaying potent anti-cancer effects against various cancer cell types." (PMID 38892310, 2024). "The knowledge structure of CDK7 inhibitors encompasses pharmacological mechanisms, therapeutic targets, and cancer treatment strategies." (PMID 39386027, 2024). "CDK7 expression is frequently dysregulated in cancer, contributing to oncogenesis by promoting uncontrolled cell proliferation and survival." (PMID 39209834, 2024). "THZ2 is an analogue of THZ1 which is a potent and selective irreversible CDK7 inhibitor with promising anticancer activity in various cancers." (PMID 38540292, 2024). "Disruption of cell cycle-regulated transcriptional programs is one mechanism by which covalent Cdk7 inhibitors have been suggested to act selectively on cancer cells." (PMID 39097586, 2024). "The intricate interplay between transcriptional regulators, including CDK7, and SEs is further highlighted by the observation that cancer cells exhibit transcriptional addiction, demanding higher transcription levels to maintain growth." (PMID 38605321, 2024). "Therapeutic application of THZ1 was further shown to inhibit patient-derived xenografts (PDXs) of TNBC, underscoring the potential of CDK7 inhibition as a promising avenue for the management of this aggressive cancer subtype." (PMID 38605321, 2024). "For the first time, we report that activation of CDK7/CDK9–Rpb1 by nuclear stress mediates transcriptional regulation to prime paraptosis in cancer cells." (PMID 38858714, 2024). "YPN-005 is a novel and selective CDK7 inhibitor with super anti-cancer activity compared to conventional THZ1." (PMID 38681203, 2024). "Despite distinctive pharmacological mechanisms, CPYPP, CsA, and curcumin were shown for the first time to induce cancer cell paraptosis in a ROS- and CDK7/CDK9-dependent manner." (PMID 38858714, 2024). "CDK7 levels are elevated in many cancer types, suggesting that cancer tissues are more dependent on CDK7 activity than normal tissues." (PMID 38540292, 2024). "We propose a novel regulatory paradigm in which the activation of CDK7/CDK9–Rpb1 by nuclear proteostatic stress mediates transcriptional regulation to prime cancer cell paraptosis." (PMID 38858714, 2024). "The highly selective covalent THZ1 (CDK7i), targeting the remote cysteine (C312) residue of CDK7, has a high sensitivity in a subset of cancers, such as T-ALL." (PMID 37443779, 2023). "Based on these results, CDK1, CDK2, CDK4, CDK5, and CDK7 are the top 5 CDKs that are highly expressed in cancer tissues compared to normal tissues." (PMID 37311884, 2023). "For example, SEs are quite CDK7-dependent, and, in cancer, the treatment of cells with the CDK7 inhibitor THZ1 reduces the recruitment of SE-driven oncogenic transcription factors and suppresses the expression of these associated oncogenes." (PMID 36960780, 2023).
cancer (continued). "It has been suggested that targeting SEs will broadly block transcriptional addiction of cancer cells, and several small-molecule inhibitors have been developed to suppress the activity of various proteins at SEs, including CDK7." (PMID 37201585, 2023). "THZ1 is a covalent inhibitor of cyclin-dependent kinase 7 (CDK7) which has demonstrated promising anti-tumor activity against various cancer types." (PMID 37627044, 2023). "Blocking CDK7 abolished the YAP-mediated induction of MMB-target genes in the MDA-MB-231 cancer cell line, which expresses high levels of endogenous YAP and is known to be addicted to YAP." (PMID 36864753, 2023). "CDK7 inhibitors (CDK7is) have significant efficacy in various preclinical cancer models with limited systemic toxicity." (PMID 37201585, 2023). "As a positive regulator of both the transcription and the cell cycle, CDK7 is an attractive target for cancer therapeutics." (PMID 36401094, 2023). "SY-1365, a selective CDK7 inhibitor, inhibited cell growth in many different cancer types at nanomolar concentrations." (PMID 37342192, 2023). "Overall, the data indicate that the top 5 CDKs, CDK1 (11/32 or 34.4%), CDK2 (10 /32 or 31.3%), CDK6 (8/32 or 25%), CDK7 (9/32 or 28.1%), and CDK19 (8/32 or 25%), are closely associated with survival probability in various cancers." (PMID 37311884, 2023). "CDK1 is significantly higher in 17 out of 24 or 70.8% of the cancers listed and CDK2 and CDK7 are higher in 16 out of 24 or 67% of the cancers listed." (PMID 37311884, 2023). "Given its role in the cell cycle and transcription, CDK7 is a promising therapeutic target in cancer." (PMID 37201585, 2023). "For example, CDK7 is a famous transcriptional addiction-related gene that affects the progression, metastasis, and prognosis of many cancers." (PMID 37171044, 2023). "By ensuring proper looping during mitosis, CDK7 protects cancer cells from DNA DSBs and excessive genomic disruption as they embark on one of their most pivotal functions, cell cycle progression." (PMID 37201585, 2023). "Deregulation of CDK7 and MED1 in cancer has been observed in many studies and linked to aggressive clinicopathological features and worse prognosis." (PMID 35158760, 2022). "SNS-032, which is a potent inhibitor of CDK7 and 9 and blocks transcription enabling-phosphorylation of RNA pol II, has antitumor activities in a broad range of human cancer cells." (PMID 35332847, 2022). "CDK7 overexpression has been observed in many cancer entities and generally indicates a worse prognosis and is associated with aggressive clinicopathological features." (PMID 35158760, 2022). "CDK7 has emerged as a target of interest in oncology due to its role in two important processes that are dysregulated in cancer cells—cell cycle and transcription." (PMID 35053461, 2022). "This uncovered both induction of NEAT1_2 splicing and poly(A) read-through similar to HSV-1 and IAV infection in cancer cells upon inhibition or knockdown of CDK7 or the MED1 subunit of the Mediator complex phosphorylated by CDK7." (PMID 36279270, 2022). "We also report evidence for further programmatic alterations, among them activation of the NF-κB pathway, compensatory in nature, that appear to determine the response of this genetically highly diverse group of cancer cells to CDK7 inhibition." (PMID 35054996, 2022). "Linear NEAT1_2 splicing, but likely also circular splicing, is also observed upon CDK7 inhibition in cancer cell lines and NEAT1_2 circRNAs are abundantly found in various blood cells in absence of de novo transcription." (PMID 36279270, 2022). "Our study revealed that MYC-driven cell cycle progression renders cancer cells with a higher sensitivity to apoptosis in response to CDK7 inhibition." (PMID 35406486, 2022). "Various studies demonstrate that cancers depend on oncogenic transcription factors and their downstream networks can be therapeutically targeted by CDK7 inhibitors of which THZ1 is the best known." (PMID 36212402, 2022).
cancer (continued). "The overabundance of CDK7 within SEs regions offer the opportunities of blockade therapies in a lineage-specific cancer cell manner." (PMID 36387198, 2022). "Our findings provide a mechanistic explanation for cooperative downregulation of cell cycle genes, illuminating the basis for novel programmatic roles of CDK7 in cancer cells." (PMID 35054996, 2022). "The selective targeting of mechanisms that promote the overall transcriptional amplification in tumor cells renders CDK7 inhibition an effective target for the treatment of cancers driven by specific oncogenes." (PMID 35757006, 2022). "Especially hemizygous copy number losses of CDK7 are more frequently observed in TNBC (72%) versus other cancers (27%), which co-occurs with losses in DNA damage response genes in the 5q13 region, such as RAD17." (PMID 36139513, 2022). "THZ1 is a highly selective covalent inhibitor of CDK7 with anti-tumor activity against multiple different types of cancer, but also inhibits CDK12 and CDK13 at higher concentrations." (PMID 36279270, 2022). "Abnormal CDK7 activation has been found in many cancers, including PCa, and CDK7 inhibitors have potent antitumor activity." (PMID 35335873, 2022). "Although not yet in clinical trials, YKL-5-124 provides a link between CDK7 inhibition and augmented antitumour immunity, and therefore represents a promising new approach in cancer immunotherapy." (PMID 35568739, 2022). "CDK7 was found to be overexpressed and promote tumorigenesis in various cancers, such as breast cancer and osteosarcoma." (PMID 36076237, 2022). "An aberrant increase of CDK7 levels has been detected in many different cancer types, e.g., gastric, pancreatic, colorectal and breast cancer, and often correlates with aggressiveness and poor prognosis." (PMID 35054996, 2022). "Since aetiological factors for sqNSCLC include first of all smoking which also applies to OSCC, ESCC, and HNSCC a comparison of CDK7 expression between these carcinoma entities is justified." (PMID 36212402, 2022). "As a result of CDK7’s direct involvement in numerous cancers, it has become an attractive target in cancer therapy." (PMID 34572383, 2021). "Authors uncovered cancer-specific kinase signatures and identified cyclin-dependent kinase 7 (CDK7) as a key regulator of EOC proliferation through the phosphorylation of polymerase II alpha (POLR2A)." (PMID 33922979, 2021). "THZ1 is the first selective and covalent CDK7 inhibitor, which shows anti-tumor effects in various cancers by inhibiting cell proliferation and inducing apoptosis." (PMID 33889549, 2021). "Several CDK7-specific inhibitors have been developed that show efficacy against a wide range of cancer types, and their antitumor activity is likely mediated through cell cycle arrest and inhibition of oncogenic transcriptional addiction." (PMID 33384381, 2021). "In accordance with previous studies indicating that CDK7 inhibitors induce cell cycle arrest and apoptosis of tumor cells via blocking the glucose consumption or interfering with cancer metabolism." (PMID 33889549, 2021). "The role of CDK7 has been reported in multiple human cancers and, therefore, is considered a promising therapeutic target." (PMID 34572383, 2021). "CDK7 inhibition with THZ1 has been shown to reduce the expression of SE-associated genes and induce global transcriptional shutdown in several cancer models, including NB." (PMID 35198433, 2021). "Cyclin-dependent kinase 7 (CDK7) regulates the cell cycle and transcription and, therefore, plays a key role in cancer development and progression." (PMID 34572383, 2021). "Inhibiting CDK7 exhibited effective cancer cell suppression which implies the potential of CDK7 inhibition to be a method for anti-cancer treatment." (PMID 34490348, 2021). "Selectively targeting CDK7 has been proven as a useful therapy for cancers that are driven by MYC amplification." (PMID 33889549, 2021).
cancer (continued). "In pancreatic cancer, CDK7 activity is particularly important for cancer cells in which MYC is upregulated, possibly due to the general increase in transcription driven by this oncogenic transcription factor." (PMID 34092037, 2021). "A number of CDK7 inhibitors are considered to be potential drug candidates for cancer therapy because they are highly cytotoxic to tumor cells only." (PMID 34109118, 2021). "CDK7 thus makes an interesting potential target for anti‐cancer therapies and the agent ICEC0942 is shown to be a potent CDK7‐specific inhibitor in both ER‐positive and TNBC cell lines." (PMID 34977868, 2021). "One main concern regarding the application of CDK7 inhibitors in cancer therapy is the variable sensitivity of different cancer types to CDK7 inhibition, which has been found in preclinical studies." (PMID 34109118, 2021). "THZ1, a covalent cyclin-dependent kinase 7 (CDK7) inhibitor, shows anti-tumor effects in various cancers by inhibiting cell proliferation and inducing apoptosis." (PMID 33889549, 2021). "Overexpression of CDK7 was documented in several cancers and it was shown to predict poor prognosis and reduced survival." (PMID 34092037, 2021). "Due to its vital role in the cell cycle as well as transcription, CDK7 has emerged as a potential target for cancer therapy." (PMID 33384381, 2021). "CDK7 has a dual role in driving the cell cycle and transcription, is upregulated in a variety of cancers and has emerged as a promising cancer therapeutic target." (PMID 32385714, 2020). "BS-181 reduced phosphorylation of CDK7 targets and impaired cancer cell line and xenograft tumour growth, establishing CDK7 as a putative cancer drug target." (PMID 32385714, 2020). "CDK7 inhibition represents a novel strategy to treat cancers with de novo or acquired resistance to other drugs, where further treatment options are limited." (PMID 32385714, 2020). "Cyclin-dependent kinase (CDK)-7 inhibitors are emerging as promising drugs for the treatment of different types of cancer that show chemotherapy resistance." (PMID 32340192, 2020). "Interest in targeting CDK7 for the treatment of cancer has been boosted by the development of a potent covalent inhibitor, THZ1." (PMID 32155786, 2020). "A recent study found that amplified super-enhancer-associated MYCN oncogene, upregulating the active transcriptional program, sensitized cancer cells to inhibition of CDK7 in neuroblastoma." (PMID 32398735, 2020). "CDK7 inhibition has been effectively tested in several aggressive cancer types, including MYCN-amplified neuroblastoma, T-cell acute lymphoblastic leukemia, triple-negative breast cancer, and small-cell lung cancer." (PMID 33299103, 2020). "RNA silencing and pharmacologic inhibitors were used to evaluate the functions of CDK7/p38α/MYC/PD-L1 axis in cancer cell proliferation and antiPD-1 therapy resistance." (PMID 32690037, 2020). "Recent reports show that THZ1, a CDK7 inhibitor, suppresses SE-associated oncogenic transcription in MYC-deregulated cancer models." (PMID 33168807, 2020). "A number of reversible and covalent inhibitors of CDK7 have been tested on large panels of cancer cell lines." (PMID 32385714, 2020). "In recent years, dysregulated TFIIH complex has been reported as a master regulatory machine in cancer progression of solid and hematologic malignancies, and the main subunit CDK7 is recognized as a druggable target in cancer treatment." (PMID 32690037, 2020). "Whilst CDK7 inhibitors are potent at impairing the growth of many cancer cell lines, representing a variety of tumour types, it is clear that some cell lines respond more favourably than others." (PMID 32385714, 2020). "We also discuss the development of selective CDK7 inhibitors, their mechanism of action in cancer and their potential for use in combination therapies." (PMID 32385714, 2020). "In this review we outline the role of CDK7 in both normal and tumour cells and the rationale for inhibiting CDK7 in cancer." (PMID 32385714, 2020).